IGKV2-29 (immunoglobulin kappa variable 2-29)
Description:
V region of the variable domain of immunoglobulin light chains that participates in the antigen recognition. Immunoglobulins, also known as antibodies, are membrane-bound or secreted glycoproteins produced by B lymphocytes. In the recognition phase of humoral immunity, the membrane-bound immunoglobulins serve as receptors which, upon binding of a specific antigen, trigger the clonal expansion and differentiation of B lymphocytes into immunoglobulins-secreting plasma cells. Secreted immunoglobulins mediate the effector phase of humoral immunity, which results in the elimination of bound antigens. The antigen binding site is formed by the variable domain of one heavy chain, together with that of its associated light chain. Thus, each immunoglobulin has two antigen binding sites with remarkable affinity for a particular antigen. The variable domains are assembled by a process called V-(D)-J rearrangement and can then be subjected to somatic hypermutations which, after exposure to antigen and selection, allow affinity maturation for a particular antigen.
Synonyms: A18; A18b; IGKV; IGKV229; IGVK-A18
Gene: Immunoglobulin variable (V) pseudogene on chromosome 2 (89,234,174 to 89,234,912, reverse strand). Ensembl gene ENSG00000253998.
Subcellular location: Secreted; Cell membrane
Diseases named in the same sentence as IGKV2-29 in open-access papers:
IGKV2-29 is named in the same sentence as 3 diseases in open-access papers, as found by Europe PMC text mining. Sharing a sentence is not in itself a finding about the gene and the disease. The quoted sentences say what the papers report.
kidney diseases (1 paper, 2024). "Proteins involved in the regulation of complement cascade (IGKV2-29 and IGHV3-23) and upregulated in the IR group aggravate AKI and its advancement to various kidney diseases." (PMID 39219798, 2024).
tumor (1 paper, 2026). "Elevated expression (consistent with tumor tissue) was noted for IGKV2-29 (FC: 4.39), a B cell/plasma cell-related gene associated with the tumor microenvironment." (PMID 41584049, 2026).
IGKV2-29 also shares sentences with these, for which no sentence is quoted: cervical cancer (1 paper).